DNMT1 (DNA methyltransferase 1)
Diseases named in the same sentence as DNMT1 in open-access papers (continued):
Sharing a sentence is not in itself a finding about the gene and the disease.
tumor (continued). "DNMT reduction via siRNA reduced β-catenin signaling by decreased methylation at several CpG loci confirming the tight interdependence between the two tumor-promoting factors DNMT1 and β-catenin." (PMID 33401659, 2021). "Mutation analysis revealed that a novel carbazole, SH-I-14, disrupted the STAT3 –DNMT1 interaction and led to the re-expression of tumor-suppressive genes such PDLIM4 or VHL, through demethylation, and showed a high anti-proliferative effect in TNBC models." (PMID 34198989, 2021). "EZH2 is also capable of recruiting DNMT1 in many cell types to methylate the promoter regions of various genes including tumor suppressors." (PMID 33572395, 2021). "Specifically, transcription level of DNMT1 was significantly higher in HNSCC tumor tissues (n = 520) than in normal tissues (n = 44, p < 0.001)." (PMID 33500531, 2021). "The epigenetic modulation of DNMT1 function via grifolin led to inactivation of tumor metastases in a metastatic mouse model." (PMID 34835969, 2021). "We found that tumours exhibiting high DNMT1 expression had markedly more infiltration of 13 TME immune cells than those exhibiting low expression." (PMID 34589490, 2021). "Among all the candidates, we focus on DNMT1 because a DNA methylation-involved regulation on CA9 has been recently suggested in a subset of tumor cells." (PMID 34493285, 2021). "A systematic bioinformatic appraisal of PPARγ and DNMT1 was performed across 29 tumor types and UM available in The Cancer Genome Atlas (TCGA)." (PMID 34439147, 2021). "As expected, subsequent enrichment analysis showed that tumours with high DNMT1 expression showed remarkable enrichment in immune activation pathways." (PMID 34589490, 2021). "Virally mediated changes to Hedgehog signaling allow for the acquisition of stem-like properties while upregulation of DNA methyltransferase 1 (DNMT1) leads to global hypermethylation and consequent epigenetic silencing of important tumor suppressors." (PMID 34638429, 2021). "Abnormal expression of DNMT1 can lead to abnormal methylation of some tumor suppressor genes CpG islands, which in turn leads to inactivation of tumor suppressor genes and cell carcinogenesis." (PMID 33616161, 2021). "The expression of DNMT1 was higher in tumour tissues than in control tissues, which was consistent with the findings in the TCGA-LIHC cohort." (PMID 34589490, 2021). "P16 is inactivated in tumours and is highly expressed in senescent cells, Rb is activated upon senescence by p21 or p16, preventing premature senescence though DNMT1." (PMID 33579350, 2021). "For example, tumours with deletions in DNA methyltransferase 1, DNMT1, had smaller TL ratios (Q = 0.028, effect size = 0.11)." (PMID 34824250, 2021). "DNMT1 is a member of the DNA methyltransferase family, responsible for the DNA methylation of cytosine-phosphoguanine (CpG) island upstream of tumor suppressor genes." (PMID 33616161, 2021). "Enhanced expression of DNMT1 in tumor tissues is a suggestive for increased aggressiveness of the disease and poor prognosis." (PMID 33604794, 2021). "Simultaneous inhibition of DNMT1/HDAC1 can play a synergistic role in improving anti-tumor drugs’ therapeutic effects and reducing the incidence of drug resistance." (PMID 34073721, 2021). "The expression level of TYMS was negatively correlated with microsatellite instability (MSI) and Tumor mutation burden (TMB), and positively correlated with methylase expression in DNMT1, DNMT2, DNMT3A and DNMT3B." (PMID 35003215, 2021).
tumor (continued). "In endometrial cancer, CAF-derived exosomal miR-148b can be transferred to cancer cells and functions as a tumor suppressor by directly binding to its downstream target gene, DNMT1, to repress tumor metastasis by inducing EMT." (PMID 35058933, 2021). "MG98 has shown interesting preclinical evidence that it can inhibit DNMT1, allowing for the re-expression of tumor suppressor genes and tumor growth inhibition." (PMID 34452630, 2021). "Western blot analysis revealed a slight DNMT1 up-regulation already in tumor-free mice, which further increased during tumor progression." (PMID 33310759, 2021). "Subsequent results in our study revealed that the expression of DNMT1 was higher in tumor samples, highlighting the correlation between DNMT1 and LAD." (PMID 33596966, 2021). "Studies on tumor growth have demonstrated the great potential of E2 in the induction of changes involving DNMT1, DNMT3A, and DNMT3B related to DNA methylation." (PMID 33915762, 2021). "Among the four types of DNA methyltransferases, DNMT1 not only participates in the normal methylation process but also induces the silencing of tumor suppressors via hypermethylation of their promoter regions." (PMID 34858853, 2021). "For the treatment of other groups, it is well established that the effects of CDK4/6 inhibitors reduce the activity of the E2F target DNA methyltransferase 1 and suppress the proliferation of tumour cells and regulatory T cells." (PMID 34059019, 2021). "Highly expressed DNMT1 is not only detected in a variety of tumor cells, but also appears before DNA methylation." (PMID 33616161, 2021). "In contrast, miRNAs from the mir-17~92a-1 cluster were identified as important tumor suppressors in PDAC; their expression was downregulated in tumor tissue via DNMT1 promoter hypermethylation." (PMID 33809566, 2021). "Accordingly, miR-140, as a tumor suppressor, controls NF-κB activity by direct targeting Dnmt1 and conducting hypomethylation and overexpression of metallothionein genes to indirectly enhance NF-κB activity in a liver cell line." (PMID 33632341, 2021). "DNA cytosine-5-methyltransferase 1 (DNMT1) acts as a crucial epigenetic modifier by regulating DNA methylation of target genes, which involves in tumor suppressor gene expression." (PMID 33500531, 2021). "The Tumor Immune Estimation Resource (TIMER) database was performed to explore the relationship between DNMT1 expression and immune-cell infiltration." (PMID 33500531, 2021). "For example, the researchers showed that inhibition of DNMT1 reduced the lung CSCs proliferation through reducing the methylation of cell cycle regulators and thus inhibited tumor growth." (PMID 34051847, 2021). "In normal fibroblast cell lines, it has little effect on DNMT1, DNMT3a and DNMT3b enzymes, while in tumor cells, DNMT1 is almost completely inhibited, and the other two enzymes are also partially inactivated." (PMID 34680038, 2021). "Intriguingly, studies on tumor growth have revealed the great potential of E2 in the induction of changes related to DNA methylation involving DNA methyltransferases (DNMT1, DNMT3A, and DNMT3B)." (PMID 33915762, 2021). "Viral interleukin-6 promotes cell proliferation, tumor invasion, and angiogenesis by suppressing caveolin 1, which plays a role in tumor development mediated by DNA methyltransferase 1 (DNMT1)-targeted STAT3 acetylation." (PMID 35008848, 2021). "The ectopic expression of DNMT1 activated primary normal breast fibroblasts and promoted their pro-carcinogenic effects, both in vitro and in orthotopic tumor xenografts whereas DNMT1 knockdown normalized breast myofibroblasts." (PMID 33498667, 2021). "After validation of miR‐135a downregulation in knockdown cells (miR‐135a KD), a significant upregulation of the DNMT1 protein and a downregulation of Nanog were observed in miR‐135a‐knockdown tumor cells." (PMID 32154082, 2020).
tumor (continued). "Inducing miR-152 and miR-148a expression can result in down-regulation of DNMT1 and consequently up-regulation of tumor suppressor genes." (PMID 33680048, 2020). "Specifically, in tumor cells, CDKi induces tumor cell stasis and down regulates DNA methyl transferase 1 (DNMT1) levels." (PMID 33193348, 2020). "Aberrantly up-regulation of DNMT1 is responsible for silencing of tumor suppressor genes in carcinogenesis." (PMID 33680048, 2020). "pre-miR-148a and pre-miR-152 decreases DNMT-1 protein expression and reduces cell proliferation; miR-148a and miR-152 expression was reduced in tumor cell xenografts in vivo." (PMID 32906681, 2020). "DNMT1 and p-STAT3 (downstream factors of RCC2) are implicated in therapeutic resistance in GBM tumor cells by functioning in an epistatic manner with RCC2." (PMID 33521058, 2020). "More evidences showed that the expression level of miR-185 decreased in carcinogenesis, in which miR-185 suppresses tumor proliferation by directly targeting DNA methyltransferase 1 (DNMT1)." (PMID 31937240, 2020). "During tumor progression, folate treatments increase expression in DNA methylation enzymes (DNMT1), decreasing tumor suppression genes." (PMID 33255538, 2020). "Curcumin was shown to induce DNA hypomethylation in several different human tumor cell lines by inhibiting the activities of DNMT1 and DNMT3B." (PMID 32878338, 2020). "High expression of DNMT1 has been observed in a variety of tumors and is a characteristic change of tumor cells." (PMID 32751889, 2020). "Using mRNA expression data from 20 primary tumor samples, we found that the mRNA expression levels of DNMT1, FOXM1, and SOX2 were significantly increased in tumor tissues." (PMID 31296961, 2020). "In nasopharyngeal primary carcinoma cells, SFN inhibited tumor growth via the downregulation of DNMT1 and re-expression of the Wnt inhibitory factor 1 (WIF1)." (PMID 32878338, 2020). "BSP analysis identified a higher methylation level of CG5 in both Huh7 and Hep3B tumor cells with DNMT1 overexpression than that in the respective control cells." (PMID 32154082, 2020). "Functional studies in mouse models of colon and prostate tumorigenesis have suggested a tumor suppressor function for Dnmt1, whose reduction resulted in increased tumor incidence." (PMID 32806509, 2020). "An example of this is the miR-29 family, which is a well-studied tumor-suppressive microRNA that targets the DNA-methyltransferases DNMT1, DNMT3A and DNMT3B in a number of tumors such as ovarian, lung, liver, melanoma, and also hematological malignancies." (PMID 32492865, 2020). "For further verification, synthesized miR‐135a agomir (Ago‐135a) or antagomir (Ant‐135a) were transfected into tumor cells (Huh7 and Hep3B), and DNMT1 expression was assessed at both the mRNA and protein levels." (PMID 32154082, 2020). "miR-148b and miR-152 overexpression inhibits cell proliferation and induces apoptosis; decreases DNMT1 expression, returns DNA methylation to normal patterns and induces re-expression of tumor suppressor genes." (PMID 32906681, 2020). "Pharmacologically-induced DNA demethylation or the knockdown of DNA methyltransferase 1 (DNMT1) expression significantly upregulated the tumor PD-L1 level under OXP treatment." (PMID 32079180, 2020). "Several studies suggest that the induction of oxidative stress mediated by hydrogen peroxide increases the activity of DNMT1 and its binding to the promoters of tumor suppressor genes as RUNX3." (PMID 32492865, 2020). "UHRF1 (ubiquitin-like containing PHD and Ring finger 1) contributed to inactivation of tumor suppressor genes by directing the binding of DNA methyltransferase 1 (DNMT1) to hemi-methylated promoters." (PMID 32290543, 2020). "A study on the identification of DNMT1 inhibitors through a virtual screening showed that 6 induces antiproliferative effects in three different tumor cell lines." (PMID 32903500, 2020).
tumor (continued). "When DNMT1 was downregulated in tumor cells, only the methylation level of CG5 was decreased, but the methylation statues of other CGs, including CG4, were not changed, suggesting the involvement of CG5 methylation in the regulation of Nanog expression." (PMID 32154082, 2020). "DNMT1 and DNMT3b cooperate for tumor suppressor silencing, and we observed a higher expression of these two proteins in K562 cells, as compared to PTPRG-expressing LAMA-84." (PMID 32225105, 2020). "They proved that NAA10 interacts with DNA methyltransferase 1 (DNMT1) thereby silencing E-cadherin, a tumor suppressor gene." (PMID 33126484, 2020). "Most importantly, we demonstrated that DNMT1 knockdown significantly repressed tumor growth in nude mouse xenograft models." (PMID 32308683, 2020). "They demonstrated that the tumor suppressive effects of miR-185 occurred via DNMT1 as overexpression of miR-185 depleted DNMT1, resulting in PTEN induction and subsequent inhibition of Akt." (PMID 31056726, 2019). "Downregulation of LUCAT1 has been linked to lower protein levels of DNMT1 and subsequent reduction of repressive methylation marks in known downstream tumor-suppressor genes under the control of DNMT1." (PMID 31658672, 2019). "Tumorigenesis was also inhibited in cell culture systems and mouse tumor models by targeting Dnmt1 with antisense oligonucleotides." (PMID 31306451, 2019). "Based upon this mechanism of action, a therapeutically effective DNA-demethylating agent needs to be incorporated into the DNA of tumor cells at a concentration that can decrease DNMT1 and allow cell cycle progression." (PMID 31370878, 2019). "The protein expression levels of the pyroptosis-related protein GSDME and DNA methyltransferases (Dnmt1, Dnmt3a, and Dnmt3b) in tumor tissues were evaluated by western blotting to explore the mechanism of the in vivo antitumor activity of As2O3-NPs." (PMID 31637008, 2019). "We examined the expression levels of 3 DNMTs, namely Dnmt1, Dnmt3a, and Dnmt3b, that are key enzymes regulating DNA methylation in specific genes, including tumor suppressor genes." (PMID 30940675, 2019). "The deubiquitylating enzyme USP7 is known to stimulate the DNMT1 activity, and conversely, USP7-siRNA reduces DNMT1 activity and decreases tumor cell viability." (PMID 30786932, 2019). "The correlation between DNM1 expression and DNA methylation in BKPyV positive tumours has not been examined, but a significant correlation between JCPyV infection increased DNMT1 expression, and DNA hypermethylation has been found in tumours." (PMID 31408949, 2019). "For example, IL-6 regulates the expression and activity of DNA methyltransferase 1 (DNMT1) leading to enhanced methylation of tumor suppressor genes." (PMID 31289620, 2019). "In summary, this study demonstrates that OCT4 is involved in tumour‐proliferative capacity by modulating DNMT1/ISL1 expression and ERK signalling pathway." (PMID 31012189, 2019). "DNA methylation, mediated by the combined action of three DNMTs (Dnmt1, Dnmt3a and Dnmt3b), has a particularly prominent role in tumor initiation, progression and specific tumor cell subsets." (PMID 31492191, 2019). "The main functions of DNMT1 in human tumor cells are maintaining gene methylation status and silencing gene expression." (PMID 29311567, 2018). "Here, the authors show that targeting of DNA methyltransferases, such as DNMT1, can potentiate anti-tumor immunity and response to checkpoint inhibition by increasing MHC gene expression and the recruitment of CD8+ T cells." (PMID 29339738, 2018). "A study revealed that inhibition of STAT3-DNMT1 (DNA methyltransferase 1) at K685 residue by novel inhibitor SH-I-14 has shown to demethylate the promoter regions of tumour suppressor genes and re-expressed PDLIM4 and VHL genes." (PMID 29298879, 2018).
tumor (continued). "The expression level of three DNA methyltransferases including DNMT1, DNMT3a and DNMT3b increased and the expression level of Tet ten-eleven translocation protein 2 remarkably decreased in tumorous spleens." (PMID 29849932, 2018). "Since alterations in DNMT1 activity are involved in tumor development and progression, drugs that interfere with this enzymes are actively researched." (PMID 30572618, 2018). "We previously reported the inverse correlation between DNMT1 expression and the tumor-suppressor microRNA-148a in liver cancer." (PMID 29700299, 2018). "The availability of this natural product will hamper tumor cell metabolic reprogramming by targeting DNMT1." (PMID 29795311, 2018). "The authors showed that DNMT1 knockdown significantly promoted the ability of 5-AZA-dC to reactivate the tumor-suppressor genes silenced by hypermethylation." (PMID 29700299, 2018). "The measurement of tumor sizes showed that the volumes of tumor xenografts from Lenti-sh-DNMT1 group were much smaller than those from Lenti-sh-NC and KYSE150 groups." (PMID 29721170, 2018). "Using immunohistochemistry assay we found a decreased expression of SOX2 in Lenti-sh-DNMT1 or 5-aza-dC treated tumor xenografts." (PMID 29721170, 2018). "hNaa10p positively regulates DNMT1 enzymatic activity by facilitating its binding to DNA and recruitment to the promoters of tumor suppressor genes such as E-cadherin." (PMID 28545228, 2017). "In this study, we demonstrated that KLF5, as a tumor suppressor, was suppressed by DNMT1-maintained hypermethylation in ccRCC." (PMID 28749461, 2017). "E6 and E7 are known to modulate the activity and the expression of DNMT1 and histone methyltransferase to down-regulate the expression of numerous tumor suppressor genes or miRNA through promoter methylation or cell signaling pathway." (PMID 28521287, 2017). "It is also reported that targeting UHRF1 and DNMT1 can affect the global methylation and re-expression of tumor suppressor genes." (PMID 29268763, 2017). "Further, de novo methylation remains in DNMT1 knockout embryonic stem cells and the role of DNMT1 in tumor methylation remains ambiguous." (PMID 28235398, 2017). "In AML, microRNA-29b targets DNMT3A and DNMT3B directly and DNMT1 indirectly thereby inducing global DNA hypomethylation and tumor suppressor gene expression." (PMID 29100357, 2017). "In recent studies, aberrant DNMT1 expression has been shown to induce miR-148a silencing and DNMT1 has been shown to be a target of miR-148a in several tumor types." (PMID 28665977, 2017). "Our study showed that 3,6-DHF effectively increases TET1 expression by inhibiting DNMT1 and DNA hypermethylation, and consequently up-regulates miR-34a in breast carcinogenesis." (PMID 28870206, 2017). "We revealed that the expression of interferon-responsive genes such as Irf7, Rig1 and Mda5 was increased by DNA methylation inhibition in tumor organoids after 5-Aza-CdR treatment or Dnmt1 knockdown." (PMID 28545228, 2017).